HIF1A (hypoxia inducible factor 1 subunit alpha)
Diseases named in the same sentence as HIF1A in open-access papers (continued):
Sharing a sentence is not in itself a finding about the gene and the disease.
prostate carcinoma (continued). "Resveratrol promoted cell death and suppressed cell survival, but its effects were overturned after HIF-1α knockdown, signifying that the effects of resveratrol in prostate cancer are mediated through HIF-1α." (PMID 35566016, 2022). "Nuclear translocation of HIF-1α was markedly increased in fibroblasts isolated from mouse prostate cancer model and deletion of HIF-1α prevented the hypoxic induction of fibroblast-to-myofibroblast differentiation." (PMID 35884382, 2022). "Treatment of human prostate cancer cells with PGE2 enhanced VEGF expression by regulating HIF-1α expression." (PMID 35842683, 2022). "LncRNA GHET1 reduces KLF2 expression to trigger HIF-1α/Notch1 signaling in increasing prostate cancer progression." (PMID 35773731, 2022). "It has been reported that CAFs up-regulate HIF1α to strengthen the malignancy and obtain stronger invasion, metastasis and anti-chemotherapeutic abilities in prostate cancer." (PMID 35589690, 2022). "The hypoxia-induced circ-0000977 modulates the immune escape of prostate cancer cells via the miR-153/HIF1A/ADAM10 axis." (PMID 35840974, 2022). "In prostate cancer, HIF-1α induced an increased expression of Forkhead box M1 (FoxM1) by binding to its promoter, while in pancreatic cancer, HIF-1α promoted PAFAH1B2 expression." (PMID 35745656, 2022). "In osteosarcoma and prostate cancer cells, ADCK2 was found to promote the TNFα-mediated accumulation of HIF-1α stability, which, in turn, is associated with the proliferation and survival of cancer cells." (PMID 35205819, 2022). "miR224 expression is significantly higher in prostate cancer tissues than in healthy prostate tissues; miR224 is increased by HIF1A overexpression and suppressed by HIF1A knockdown, indicating that it is upregulated under hypoxia via HIF1A." (PMID 35659268, 2022). "Expression of HIF-1α in normal prostate tissues and different grade groups of prostate cancer tissues." (PMID 34220956, 2021). "Pristimerin has been reported to inhibit the expression of HIF-1α and hypoxia-induced progression in hypoxic PC-3 prostate cancer cells." (PMID 34026649, 2021). "It has been shown that MSA inhibits the expression and activity of HIF-1α in invasive rat and human prostate cancer cells." (PMID 34205571, 2021). "We have also found that knockdown of CDK4 in combination with HSP90 inhibition inhibited the level of HIF1α in PC3 prostate cancer cell line." (PMID 34686682, 2021). "The AKT/ PI3K pathway and PTEN/PI3K signaling pathways regulate expression of VEGF and HIF-1α in prostate cancer cell lines." (PMID 34011277, 2021). "Although overexpression of HIF-1a and/or HIF-2a is associated with poor survival in many other types of cancer including colorectal, breast, and prostate cancers, HIF1α has been identified as a suppressor gene for kidney cancer located in 14q." (PMID 34218253, 2021). "Hypoxia and the hypoxia-induced expression of the transcription factors HIF-1α or HIF-2α promote bone metastasis of prostate cancer, for example, via upregulation of CXCR4." (PMID 34064589, 2021). "Hypoxia-inducible miR-182 accelerates tumor angiogenesis and growth by regulating the expression level of HIF1α in prostate cancer cells." (PMID 34650600, 2021). "Similar synergistic activity of MSA in combination with docetaxel was shown in a model of prostate cancer cells, which can also be explained by the inhibition of HIF-1α by the activation of PHDs." (PMID 34205571, 2021). "Reports suggested that propofol reduced HIF-1α expression in prostate cancer and non-small-cell lung cancer cell lines." (PMID 34351978, 2021). "It has been reported that upregulation of CDCA2 regulated by HIF-1α inhibited apoptosis and promoted proliferation in prostate cancer." (PMID 34545328, 2021). "CDCA2 promotes cell proliferation in prostate cancer and is known to be directly regulated by the HIF-1α pathway." (PMID 33637686, 2021).
prostate carcinoma (continued). "Co-relationship of HKII level with HIF-1α expression in normal prostate tissues and different grade groups of prostate cancer tissues." (PMID 34220956, 2021). "Bone marrow adipocytes can also promote the activation of HIF-1α in metastatic prostate cancer cells, resulting in metastatic cells acquisition of the Warburg effect phenotype." (PMID 33926551, 2021). "Co-immunoprecipitation assays have confirmed a direct interaction between AR and HIF1α, and ChIP analysis showed HIF1α interacts with the AR in genes involved in prostate cancer." (PMID 33784295, 2021). "Inhibition of SENP1 expression in high-grade metastatic prostate cancer cells can affect the bone remodeling ability of HIF-1α and its downstream matrix metalloproteinase (MMP)-2 and MMP-9, and then inhibit the bone metastasis of prostate cancer cells." (PMID 33791211, 2021). "In this sense, in prostate cancer cells overexpressing HIF-1α, irradiation leads to a re-assortment in favor of G0/G1 and S-phase, in accordance with CHK1 phosphorylation and p21 up-regulation." (PMID 34539584, 2021). "On the one hand, HIF1α is a key transcription factor responsible for inducing PRKAR2B expression in prostate cancer." (PMID 33025691, 2020). "Data from human prostate cancer cell lines supported the influence of propofol on prostate cancer cell growth and survival via reducing hypoxia-inducible factor (HIF)-1α expression." (PMID 32182262, 2020). "This study demonstrated that hypoxia increased TRPM7 expression and simultaneously induced HIF-1α accumulation as well as EMT in androgen-independent prostate cancer cells." (PMID 32215176, 2020). "HIF-1α protein expression was determined by western blotting to validate the hypoxic condition exposed in androgen-independent prostate cancer cells." (PMID 32215176, 2020). "We observed that Annexin A1 protein expression was increased by hypoxia in androgen-independent prostate cancer cells, which was inhibited by knockdown of both HIF-1α and TRPM7." (PMID 32215176, 2020). "In prostate cancer, the inhibition of HIF‐1α by agents that target the PI3K/PTEN/AKT/FRAP pathways contribute to therapeutic efficacy." (PMID 32436609, 2020). "In prostate cancer, the HIF-1α is expression regulator of S100A8/A9, which play important roles during tumorigenesis, affecting inflammatory processes, proliferation, invasion, and metastasis of tumor cells." (PMID 32509575, 2020). "The promotive role of overexpressed HIF1α in radioresistance has been elaborated in prostate cancer cells, the mechanism of which was found to be by inducing β-catenin nuclear translocation." (PMID 33304897, 2020). "For example, choline kinase (Chk) contributes to malignant transformation and progression of prostate cancer and is controlled by HIF-1α signaling." (PMID 32509575, 2020). "The oncogenic AR, hypoxia and HIF1a pathways support prostate cancer development through independent signaling pathways and transcriptomic profiles." (PMID 32450824, 2020). "The previous study revealed that Annexin A1 was upregulated by HIF-1α overexpression induced by hypoxia and played an essential role in prostate cancer." (PMID 32215176, 2020). "Our western blot results showed that knockdown of HIF-1α inhibited EMT change of androgen-independent prostate cancer cells induced by hypoxia in both PC3 and DU145 cells." (PMID 32215176, 2020). "AR and hypoxia/HIF1a signaling pathways independently promote prostate cancer progression and therapeutic targeting of both pathways simultaneously is warranted." (PMID 32450824, 2020). "Our previous study shows that ERRα can function to promote the hypoxic growth adaptation of prostate cancer cells via its direct interaction with HIF-1α and enhancement of HIF-1 signaling." (PMID 32226548, 2020). "Hypoxia simultaneously increased TRPM7 expression and induced HIF-1α accumulation in androgen-independent prostate cancer cells." (PMID 32215176, 2020).
prostate carcinoma (continued). "This suggested that Annexin A1 downregulation mediated the suppression of EMT induced by HIF-1α knockdown in androgen-independent prostate cancer cells." (PMID 32215176, 2020). "For instance, normoxic expression of HIF1α is correlated to the development of radioresistance of prostate cancer cells." (PMID 33304897, 2020). "SENP1 can regulate MMP-2 and MMP-9 through the HIF1α signaling pathway, thereby promoting the progression of prostate cancer cell lines and bone metastasis." (PMID 33123273, 2020). "Here we revealed that PRKAR2B can facilitate tumour glycolysis by increasing HIF‐1α, which is commonly overexpressed in prostate cancer." (PMID 33025691, 2020). "HIF-1α upregulation by bafilomycin A in PC3 prostate cancer cells was pHi independent, in congruence with the lack of effect of a3 KD on pHi in our study." (PMID 32085585, 2020). "This was also supported by previous study showing silibinin inhibited HIF-1α expression in prostate cancer cells." (PMID 32801360, 2020). "Previous studies have shown that SENP1 is highly expressed in human prostate cancer specimens and is correlated with the expression of hypoxia-inducible factor 1α (HIF1α)." (PMID 33123273, 2020). "HIF-1α also facilitated the regulatory loop with integrin-linked kinase (ILK) to promote epithelial-mesenchymal transition in breast and prostate cancer cell lines." (PMID 32322559, 2020). "The Spearman correlation analysis suggested the HIF-1α expression to be significantly associated with increased MDR1 and LAPTM4B expression in breast, ovarian, colon and prostate cancer patients." (PMID 30746305, 2019). "Hypoxic prostate cancers, which induce HIF1α and glycolysis most strongly, tend to be of higher Gleason grade, are more invasive and metastatic, and less responsive to therapy than those with normal oxygen levels." (PMID 30813322, 2019). "To assess the potential role of HIF1α on autophagy pathway in the prostate cancer, we first examined the protein levels of autophagy markers under hypoxic culture condition." (PMID 31700698, 2019). "We evaluated the expression levels of SHMT2, PKM2, and HIF-1α in prostate cancer tissues with different Gleason scores collected from human patients." (PMID 31500219, 2019). "Our results showed similar findings compared to previous studies on the expression of HIF-1α in prostate cancer." (PMID 30746305, 2019). "They showed that HIF-1α was highly expressed in 90% of colon, breast, and prostate cancer tissues compared to normal tissue." (PMID 33817155, 2019). "Association analysis between HIF-1α, MDR1 and LAPTM4B expression in prostate cancer blood specimens." (PMID 30746305, 2019). "Previous studies have shown that HIF-1α is expressed in various tumor tissues from liver, breast and prostate cancers." (PMID 33817155, 2019). "Others found that silibinin targeted the onset of angiogenesis in prostate cancer and inhibited signalling originated by Hypoxia-inducible factor 1-alpha (HIF-1α)." (PMID 31727143, 2019). "Here, we explored the relationship between hypoxia and autophagy and further evaluated the regulative role of HIF1α on autophagy pathway in prostate cancer." (PMID 31700698, 2019). "Serum concentrations of HIF-1α have been studies elsewhere in Graves’ disease as well as in case of prostate cancer." (PMID 30746305, 2019). "This meta-analysis was performed to evaluate the relationship between hypoxia-inducible factor-1α (HIF1α) 1790G/A gene polymorphism and the susceptibility to renal cell carcinoma (RCC) and prostate cancer (PCa)." (PMID 31419966, 2019). "We proved that combined docetaxel with propofol enhanced sensitivity under hypoxia condition in prostate cancer cells, and it was related to HIF-1α expression." (PMID 29568752, 2018). "Supporting this notion, radiation has been found to induce HIF-1α expression in a number of tumor cell lines, including the prostate cancer DU145 cell line." (PMID 29921791, 2018).
prostate carcinoma (continued). "In this work, HIF-1α expression was found to be correlated with androgen sensitivity among prostate cancer cell lines, and the difference was attributable to the factor’s translation efficiency." (PMID 29921791, 2018). "On the other hand, high expression of MAOA in human tissues correlates with poor prognostic in prostate cancer patients and increased tumor metastasis in xenograft mouse model of prostate cancer via HIF1-α/VEGF-A/FOXO1/TWIST1 signaling pathway." (PMID 29334991, 2018). "As thapsigargin decreases HIF1α levels and activity we examined if prostate cancer cell lines were more sensitive to thapsigargin in hypoxic cells." (PMID 29529249, 2018). "To explore the mechanism underlying EMT and hypoxia-induced docetaxel resistance due to HIF-1α overexpression in prostate cancer cells, we knocked down HIF-1α and examined E-cadherin and vimentin expression using western blotting." (PMID 29568752, 2018). "Our recent study shows that ERRα promotes the hypoxic growth adaptation of prostate cancer cells via a mechanism of direct interaction with HIF-1α and augmentation of HIF-1 signaling." (PMID 30042415, 2018). "In fact, HIF-1α has been previously reported to be a key survival factor for serum- or oxygen-deprived prostate cancer cells." (PMID 29162859, 2017). "QRT-PCR showed a trend toward prostate cancer cell lines having higher HIF-1a and TCF12 mRNA expression than the normal prostate cell line (p < 0.05)." (PMID 29069829, 2017). "This makes hypoxia one of the most common features within the microenvironment of solid tumors, and hypoxia responsive HIF-1α level is found to be particularly elevated in many human solid tumors including colon, gastric, lung, and prostate cancers." (PMID 28841148, 2017). "For example, the member of the basic helix-loop-helix/PAS (bHLH/PAS) transcription factors SIM2s, has been shown to attenuate BNIP3 hypoxic induction via cross-talk with HIF-1α on the HRE in prostate cancer cells." (PMID 28968982, 2017). "The clinical importance of HIF-1α expression in prostate cancer has been demonstrated and HIF-1α has been examined as a potential prognostic marker, being elevated in high grade PIN and not BPH." (PMID 28394264, 2017). "In particular, the contribution of hypoxia in the increased expression of miR-21 and the capability of this miRNA to induce angiogenesis through HIF-1α expression have been reported by in vitro studies on pancreatic and prostate cancer cells, respectively." (PMID 29221165, 2017). "In prostate cancer, inhibition of estrogen receptor β or hypoxia can stabilize HIF-1α which can contribute to the transcription of IKKβ, resulting in the activation of NF-κB." (PMID 28173803, 2017). "Studies have shown that a causal relationship are observed between the expressions of β-AR and HIF-1α in pancreatic, breast and prostate cancer cells." (PMID 28977119, 2017). "In our study, HIF-1α expression was induced by hypoxia in human prostate cancer, confirming findings of previous studies and suggesting a key role of HIF-1α in prostate cancer within a hypoxia microenvironment." (PMID 28760843, 2017). "ERRα augments HIF-1 signaling by directly interacting with HIF-1α in normoxic and hypoxic prostate cancer cells." (PMID 29214989, 2017). "Prostate carcinoma triggers an increase in hypoxia, which regulates HIF1A that in turn impacts downstream the expression of LOX, CAIX and VEGFR2 in tumor cells." (PMID 28143503, 2017). "Prostate cancer cells co-cultured with adipocytes switch to a high glycolytic rate, increasing HIF1α production in an oxygen independent manner." (PMID 28270771, 2017). "For prostate carcinoma and other oncologic models, besides the observed higher amount of HIF-1α in tumors, increased HIF-1α expression was also associated with prognosis." (PMID 28143503, 2017). "In the present study, we aim to investigate the effect of atorvastatin on HIF-1α expression and radiosensitivity in prostate cancer cells." (PMID 28760843, 2017).
prostate carcinoma (continued). "In pre-clinical studies, digoxin has been shown to inhibit HIF-1α in prostate cancer cell lines at concentrations of 100 nM and prostate cancer cell proliferation at 23–255 nM." (PMID 28591151, 2017). "To substantiate this observation, we compared the levels of PHF8, HIF1α and HIF2α in pre- and post-castration prostate cancer tissues from 14 patients with advanced prostate cancer by western blot analysis." (PMID 27991916, 2016). "Previous studies demonstrate that β-arr1 interacts with HIF-1α in breast and prostate cancer cells under hypoxic condition." (PMID 26909598, 2016). "Cells treated with inhibitors of PI3K and mTOR or transiently transfected with dominant negative AKT or PI3K have been reported to inhibit HIF-1α expression in human prostate cancer cell lines." (PMID 26882567, 2016). "Through mechanisms not completely defined, β-arr1 has been found to physically interact with HIF-1α in the nucleus of breast and prostate cancer cells under hypoxia stimuli." (PMID 26909598, 2016). "The results we have yielded provide the mechanism for inhibitory action of HIF-1α and angiogenesis by pristimerin in hypoxic prostate cancer cell lines." (PMID 27581969, 2016). "Our study showed that SPHK-1 and HIF-1α accumulations began to increase after 30 min of hypoxia exposure in PC-3 prostate cancer cells compared with the normoxia, which is consistent with previous studies." (PMID 27581969, 2016). "Our previous data obtained from prostate cancer cells, ovarian cancer cells and renal carcinoma cells indicated that isoflurane up-regulates the synthesis of HIF-1α via the PI3K/Akt/mTOR pathway and promotes the metastatic potential of cancer." (PMID 27028996, 2016). "In a study with a flank tumor model of PC-3 human prostate cancer, acriflavine prevented tumor growth and arrested tumor vascularization - a process that HIF-1α regulates in cancer biology." (PMID 26962408, 2016). "This peroxide-induced stabilization of HIF-1α increases proliferation, invasiveness, and metastasis of prostate cancer cells." (PMID 26689994, 2016). "Overall, in our paper, we provide the first mechanistic link between mTOR inhibition and docetaxel resistance in prostate cancer implicating the regulation of HIF-1α/SK1 pathways." (PMID 27821815, 2016). "Additional studies of KDM3A revealed that its demethylation of H3K9me2/1 facilitates the transcriptional activity of AR, and HIF1α in responding to hypoxia in prostate cancer cells." (PMID 27689328, 2016). "Under hypoxic conditions HIF-1α dependent signaling promotes epithelial to mesenchymal transition (EMT) in prostate cancer cells which is proven to play a role in cancer progression and invasiveness." (PMID 27975057, 2016). "Here, we demonstrate that pristimerin inhibits HIF-1α via the SPHK-1 signaling pathway in a prostate cancer cell lines." (PMID 27581969, 2016). "HIF-1α is increased in prostate cancer and thus drive the transcription of hypoxia-adaptive under both hypoxia and normoxic conditions." (PMID 26919249, 2016). "The clinical importance of our findings is supported by data showing increased HIF-1α levels in primary prostate cancer and its key role in disease progression." (PMID 27821815, 2016). "Together, these results suggest that castration treatment can lead to local ischemia/hypoxia in prostate cancer tissues and a concurrent up-regulation of HIF1α and HIF2α as well as PHF8." (PMID 27991916, 2016). "Expression of NANOG, particularly in conjunction with HIF-1α, was proposed as a biomarker for prostate cancer." (PMID 27764770, 2016). "A recent study reported that pristimerin suppressed HIF-1α and hypoxia-induced metastasis in prostate cancer PC-3 cells." (PMID 27581969, 2016). "In a recent report, TRPM8-promoted hypoxic tumor growth in AR+ prostate carcinoma cells involves RACK1 binding to HIF-1α and RACK1-mediated ubiquitination of HIF-1α." (PMID 26512697, 2015).